CAV1 (caveolin 1)
Diseases named in the same sentence as CAV1 in open-access papers (continued):
Sharing a sentence is not in itself a finding about the gene and the disease.
tumor (continued). "Cells within the invading tumor islands/clusters were occasionally positive for both cytokeratin and CAV1." (PMID 25633184, 2015). "To evaluate the role for Cav-1 in PC cell invasion, we depleted Cav-1 from cells with siRNA or shRNA and performed Transwell invasion assays and wound healing (scratch) assays to evaluate the role of Cav-1 in these important tumor cell functions." (PMID 26065715, 2015). "In our study, we observed equal amounts of caveolin-1 in tumor and normal tissues in 25% of samples, while in the others it was down-regulated." (PMID 24533441, 2014). "Positive staining was defined as membranous and/or cytoplasmic in reactive tumor cells for phospho-Met, and phospho-CAV1." (PMID 25148256, 2014). "The evidence for the dysregulation of miR-133a during metastasis is similar to CAV1 in that it is reactivated during metastasis since its expression changes during tumor progression." (PMID 25104873, 2014). "Studies have shown a strong correlation between CAV1 up-regulation and increased tumour grade, invasiveness, and regional metastasis and decreased overall survival in the bladder, oesophageal, and CaPs." (PMID 25228915, 2014). "Caveolin-1, through phosphorylation and/or dephosphorylation, interacts with signaling molecules, and regulates tumor cell proliferation, apoptosis, adhesion and movement." (PMID 24932304, 2014). "Conversely, knockdown of CAV1 in metastatic HCC cells markedly inhibited the tumour metastatic potential in vivo." (PMID 25180681, 2014). "Tumor growth was significantly accelerated in mice injected with Cav-1 overexpressing RD cells, yielding huge tumor masses characterized by a visible increased vascularization and a weight of about 4 times higher compared to controls." (PMID 24427291, 2014). "The overall survival rate has also been found to decrease with the deregulation of tumor stromal Cav-1." (PMID 25202343, 2014). "The functional interaction between AhR and Cav-1 likely has an important contribution to the motility of mesenchymal cells, and emphasizes the relevance of both proteins in the migration of tumor cells." (PMID 25238970, 2014). "Consistent again with the notion that CAV1 functions as a tumour suppressor, tumours formed by B16F10 (cav-1) cells were smaller in comparison with B16F10 (mock) cells at the initial site of tumour growth before surgery (compare Fig. 4f1 and f2, respectively)." (PMID 24500501, 2014). "Certain reports have insisted the tumor suppressive functions of Cav-1 by knockout of the CAV1 gene in cells with a luminal phenotype." (PMID 25202343, 2014). "Cav-1 and Rho/ROCK signaling is known to promote the migration and metastasis of tumor cells by regulating FA dynamics through the tyrosine (Y14) phosphorylation of Cav-1." (PMID 25202343, 2014). "Other study has also demonstrated that tumors with upregulated Cav-1 exhibit a positive correlation with tumor diameter and tumor grade/stage (pTNM and pM stages)." (PMID 25202343, 2014). "Our results strongly suggest that CAV1 mediates tumor suppression, at least in part, by turning tumor cells more prone to differentiate." (PMID 25313138, 2014). "These tumours were also characterised by increased tyrosine phosphorylation of Ptrf/cavin, which is localised with Cav1 to caveolae, and of the RTK Axl and the docking protein Dock1." (PMID 25200860, 2014). "Quantitative evaluation performed after normalization confirmed the results; overexpression of caveolin-1 and flotillin-1 was recorded in most tumor samples compared to control ones." (PMID 25243186, 2014). "The downregulation of the tumor biomarkers caveolin-1 and Acsvl3 suggests a reduction of tumor growth." (PMID 25015569, 2014). "Caveolin-1 (CAV1), encoding the structural component of cellular caveolae, is a suggested tumor suppressor gene involved in cell signaling." (PMID 25313138, 2014).
tumor (continued). "Despite the contradictory views of the clinical role of Cav-1 expression in several types of cancer, the upregulation of Cav-1 in human cancer cells serves as a tumor promoter role in the majority of human cancer types." (PMID 25202343, 2014). "We also investigated the relationship of age, sex, histological grade, and tumor size with stromal Cav-1 expression." (PMID 24949874, 2014). "As a result caveolin-1 can affect cell proliferation, programmed cell death, migration and other processes important for tumor transformation and progression." (PMID 24533441, 2014). "TMPRSS2-ERG was found to associate with these factors in a manner predicting a poor outcome of the patient (high tumor stromal expression of PDGFRβ, hyaluronan, von Willebrand factor and low stromal expression of Caveolin-1)." (PMID 24505269, 2014). "The theory of ‘the autophagic tumor stroma model of cancer metabolism’ is a newly established model to understand the prognostic value of the downregulation of stromal Cav-1." (PMID 25202343, 2014). "Consistent with a role for CAV1 as a tumour suppressor, tumour formation of B16F10 (cav-1) cells was delayed compared with B16F10 (mock) cells at all time points (data not shown)." (PMID 24500501, 2014). "Evidence is available indicating that Cav-1 promotes migration in a variety of cells, including fibroblasts, endothelial cells and tumor-derived cell lines." (PMID 25202343, 2014). "Our study provides the first initial evidence for the tumor promoting activity of Cav-1 through CSC regulation." (PMID 24939878, 2014). "Caveolin-1, a tumor suppressor is the major structural protein of caveolae and plays a critical role in the regulation of various physiological and pathological processes such as cardiovascular diseases, cancers and neurological disorders." (PMID 25594072, 2014). "The correlation between GLI1 and Cav-1 was confirmed in tumor specimens from HCC patients and Cav-1 was found to be associated with poor prognosis after hepatic resection." (PMID 24454730, 2014). "In this study we found wild type BRCA1/1a proteins to induce expression of caveolin-1, a tumor suppressor in BRCA1-mutant serous epithelial ovarian cancer (SEOC) cells by immunofluorescence analysis." (PMID 25594072, 2014). "Caveolin-1 (Cav-1) can ambiguously behave as either tumor suppressor or oncogene depending on its phosphorylation state and the type of cancer." (PMID 24427291, 2014). "On the other hand, the enhanced expression of CAV1 playing a tumor suppressive role in HCC has been also reported." (PMID 25148256, 2014). "In the present study, the expression and clinical role of Cav-1 were analyzed in tumor stromal and human cancer cells, respectively." (PMID 25202343, 2014). "Briefly, a crosstalk between HIF-1α and Cav-1 induces autophagy/mitophagy in the tumor stroma, and consequently provides cancer cells with essential amino acids and nucleotides to drive tumor growth and metastasis." (PMID 24978438, 2014). "Augmented CAV1 expression suppresses tumour formation upon a subcutaneous injection, but enhances lung metastasis of cells injected into the tail vein in both models." (PMID 24500501, 2014). "We analyzed the correlation of stromal Cav-1 expression with clinicopathologic features and prognostic indicators, such as tumor marker HER-2/neu gene." (PMID 24949874, 2014). "The mRNA level of Cav-1 was significantly degraded in laser-captured tumor stroma samples compared with the paraneoplastic and normal tissue (P<0.05)." (PMID 24949874, 2014). "Having demonstrated that Cav-1 contributed to CSC regulation and malignancy induced by chronic SWCNT exposure in vitro, we determined the role of Cav-1 in tumor growth and progression in vivo." (PMID 24939878, 2014). "Available evidence indicates that caveolin-1 is a multifunctional scaffold protein that function, depending on the cellular settings, both as tumor suppressor and promoter." (PMID 25397596, 2014).
tumor (continued). "In NSCLC reports about tumor promoting vs. tumor suppressive roles of CAV1 are conflicting and vary among different cell lines used." (PMID 25222296, 2014). "The maximum of approximately 4-fold tumor induction was observed with Cav-1-overexpressing cells over control cells, substantiating the tumor promoting role of Cav-1." (PMID 24939878, 2014). "Contrasting functions of Cav-1 have been demonstrated; a tumor suppressor function and an oncogenic role." (PMID 25202343, 2014). "Our data showed that Cav-1 not only promoted tumor formation but also metastasis of the tumor cells to neighboring tissues." (PMID 24939878, 2014). "At day 38 after injection, tumour volumes were 268±232 and 1596±247 mm3 for A375 (cav-1) and A375 (mock), respectively." (PMID 24500501, 2014). "Positive Cav-1 expression was found to correlate with tumor diameter (P=0.0079), histopathological grade (P=0.0272) and poor prognosis (P=0.0008)." (PMID 25202343, 2014). "Experimentally, an up-regulation of Cav-1 was shown to potentiate various steps in tumor progression, metastasis and chemoresistance, anchorage-independent growth (anoikis resistance), and cell migration and invasion." (PMID 24939878, 2014). "PTRF also attenuates the effect of pro-tumor caveolin-1, leading to suppression of tumor growth and metastasis." (PMID 24747515, 2014). "An improved understanding of Cav-1 expression in tumor stromal and cancer cells will increase knowledge with regard to the clinical value of Cav-1 and its detailed mechanisms." (PMID 25202343, 2014). "Caveolin-1 seems to demonstrate both tumor suppressive and oncogenic activity depending on the cellular settings." (PMID 25397596, 2014). "In vivo, CAV1-expressing tumor cells show growth delay and higher muscular differentiation in comparison to untransfected and vector transfected cells." (PMID 25313138, 2014). "Caveolin-1 (CAV1) has been attributed roles as a tumour suppressor, although in late-stage tumours, its presence is associated with enhanced metastasis." (PMID 24500501, 2014). "Cav-1 has been suggested to act either as a tumor suppressor or as an oncogene, depending on the tumor type and/or tumor stage." (PMID 24949874, 2014). "Due to the crucial roles of CAV1 and MMPs in regulating tumor progression and metastasis, a growing number of studies have investigated a possible relationship between these molecules." (PMID 25180681, 2014). "In clinically confined RCC we investigated the correlation between Cav-1 and pERK-1/2 levels in primary tumours and sought to examine if their combined expression provided an enhanced prognostic indicator." (PMID 24119769, 2013). "Concordance of Cav-1 and pERK-1/2 expression was assessed for 16 available matched primary and secondary (mRCC) tumours obtained from 14 different patients; in two patients mRCC tissue was available from two sites." (PMID 24119769, 2013). "The Cav1 role in radio- and chemoresistance of tumour cells also provides rationale for targeting Cav1 in cancer." (PMID 23521716, 2013). "For the combined covariate of Cav-1/pERK-1/2, the primary and secondary tumours pairs were 88% (14/16) concordant." (PMID 24119769, 2013). "This would explain why the major effect observed in endothelial cells as a consequence of CAV1 silencing in tumor cells was reduced migration." (PMID 23951165, 2013). "RCC is a highly vascular tumour and previous studies have shown a significant positive correlation between tumour Cav-1 levels and high microvessel density." (PMID 24119769, 2013). "Our results identified caveolin-1 (CAV1) as significantly up-regulated in myeloid cells in the presence of GBM tumor cells." (PMID 24130882, 2013). "The relationship between the tumour angiogenesis promoted by Cav1 and the enhanced metastatic potential of a neoplastic clone has yet to be elucidated." (PMID 23521716, 2013).
tumor (continued). "It was in contrast to the other study which showed that the low expression of tumor cells Cav-1 protein was correlated with high T stage, TNM stage and lymph node metastasis." (PMID 23527097, 2013). "Although Cav1 is likely to behave as a tumour suppressor protein in early phases of tumour onset, growing evidence suggests that more advanced or metastatic tumours have Cav1 activation." (PMID 23521716, 2013). "The recent discovery of Cav1 as a metastasis promoter has challenged its role as biomarker of tumour progression." (PMID 23521716, 2013). "All 286 GC samples were available for analysis of Cav-1 immunostaining in tumor cells and 247 (86.4%) cases had sufficient tissues for analysis of Cav-1 immunostaining in CAFs." (PMID 23527097, 2013). "The strong intensity doughnut-shaped positive signal of Cav-1 in the tumour stroma was the internal control of endothelial expression." (PMID 23527097, 2013). "Cav-1 absence sensitizes mouse skin to carcinogen induced epidermal hyperplasia and tumor formation." (PMID 23580232, 2013). "Analysis of the levels of a group of pro-angiogenic factors released by tumor cells showed that only the expression of the bFGF gene was reduced by CAV1 silencing." (PMID 23951165, 2013). "Targeting vascular endothelium is a relatively novel approach to tumour therapy, and the selective endocytosis mediated by Cav1 represents one of the most promising current strategies to achieve localized gene expression and direct damage of endothelial cells." (PMID 23521716, 2013). "Using three human RCC cell lines derived from tumours of clear cell origin we found Cav-1 promoted invasiveness in all the models examined irrespective of genetic background of the cell line." (PMID 24119769, 2013). "Multivariate Cox regression analysis found only tumour grade (HR = 3.4; P = 0.001), capsular invasion (HR = 5.4; P < 0.001) and combined expression of Cav-1 and pERK-1/2 (HR = 4.2; P < 0.001) showed significant association with reduced DFS." (PMID 24119769, 2013). "TGF-β was shown to enhance tumor growth under certain conditions and has recently been demonstrated to increase caveolin-1 expression in the pluripotent human embryonic carcinoma cell line NT2/D1 as well as in murine mammary epithelial cells (NMuMG)." (PMID 23339737, 2013). "The combined expression of Cav-1 and pERK-1/2 correlated with clear cell histology, high tumour stage and vascular invasion." (PMID 24119769, 2013). "We showed a high proportion of metastatic tumours to be Cav-1 positive (69%), a result consistent with the previous small case study of Hayakawa and co-workers reporting Cav-1 expression in 83% (5/6) of secondary tumours." (PMID 24119769, 2013). "Loss of Cav-1 protein in CAFs promotes the activation of CAFs via activating TGF-β pathway, therefore facilitating the tumor microenvironment remodeling and tumor development." (PMID 23527097, 2013). "Many regulatory proteins were identified as tumor suppressor or tumor promoter proteins; however, in the case of Cav-1, both functions were reported." (PMID 23460862, 2013). "The major structural protein in caveolae is caveolin-1, which is known to act as a key regulator in cancer onset and progression through its role as a tumour suppressor." (PMID 23521716, 2013). "Beside, Cav1 phosphorylated on tyrosine 14 contributes to adhesion maturation and tumour cell migration through a crosstalk with galectin-3." (PMID 23521716, 2013). "Since Cav-1 protein is the requisite structural component of caveolae, altered expression of Cav-1 protein in CAFs would impact various pathological processes and consequently promote tumor development." (PMID 23527097, 2013). "Cross tabulation revealed the levels of Cav-1 and pERK-1/2 to be significantly (P = 0.03) associated in the primary RCC tumours with 19% (29/158) of tumours showing co-expression." (PMID 24119769, 2013).
tumor (continued). "H&E staining showed a reduced number of vessels and a major incidence of necrosis in tumor sections from CAV1 knocked down cells." (PMID 23951165, 2013). "In contrast, in vivo experiments showed that Met-1 cells (a mouse luminal mammary epithelial cell line) harbouring Cav1-1P132L formed tumours that were larger than Met-1 cells with wild-type Cav1 and had a greater metastatic potential." (PMID 23521716, 2013). "Apart from its signaling function in normal cells, caveolin-1 also functions as a tumor suppressor and pro-apoptotic protein." (PMID 23714181, 2013). "High Cav1 expression correlated with poor tumour differentiation, advanced tumour stage and distant metastasis." (PMID 23521716, 2013). "In prostate, it was reported that stromal factors, such as caveolin-1 and thymidine phosphorylase were related with tumor aggressiveness." (PMID 24073251, 2013). "A recently developed cell-permeable peptide, derived from the amino acids of the CSD of Cav1 and termed cavtratin, has been shown to reduce microvascular hyperpermeability and to delay tumour progression in mice by inhibiting eNOS." (PMID 23521716, 2013). "Nevertheless, there is a growing interest in secreted Cav1 as a biologically active molecule that promotes cell survival and angiogenesis within the tumour microenvironment." (PMID 23521716, 2013). "In conclusion, our study evaluated the Cav-1 expression in both tumor cells and CAFs and investigated their clinical significance for GC patients." (PMID 23527097, 2013). "In this current study we show in primary RCC tumours correlation between the increased expression of pERK-1/2 and Cav-1, and that their combined expression serves as a more powerful predictor of disease recurrence than tumour stage or pERK-1/2 or Cav-1 alone." (PMID 24119769, 2013). "In agreement with previous results, CAV1 silencing resulted in significant tumor growth reduction in all three models (P≤0.05)." (PMID 23951165, 2013). "For example, the elevated levels of Cav-1 in clinical tumour tissue from prostate, bladder and multiple myeloma is unequivocally linked with metastasis and poor prognosis." (PMID 24119769, 2013). "We report a significant concordance in the expression of Cav-1 and pERK-1/2 between primary tumours and matched metastatic tissue which supports the use of localised tumour biology to guide therapy of non-resectable mRCC." (PMID 24119769, 2013). "In early studies, Cav1 expression was reported to be down-regulated in a wide range of human tumours and cell lines, which hinted at its tumour suppressor abilities." (PMID 23521716, 2013). "Although Cav-1 failed to completely co-localize with either cytokeratin 5 or cytokeratin 14, most of the Cav-1 positive cells were found in regions of the tumor were there was an abundance of cytokeratin 5 or cytokeratin 14 positive cells." (PMID 22356861, 2012). "Because hypermethylation in promoter regions of tumor suppressor genes is often induced by viral infection, and inactivation of tumor suppressors is a major cause of carcinogenesis, we hypothesized that HBx might regulate caveolin-1 expression by a similar mechanism." (PMID 22894556, 2012). "We performed Western blotting analysis on molecules whose expressions were changed in relatively a large number of tumor tissues, including cyclin B1, caveolin 1, collagen VI, ACC1/pS79, CHK2, and IGFBP2." (PMID 22348039, 2012). "Caveolin-1 is of special interest, since it is known to promote cell migration, invasion and is proposed to be involved in tumor cell metastasis." (PMID 22505999, 2012). "On the one hand, evidence is available indicating that caveolin-1 promotes migration in a variety of cells including fibroblasts, endothelial cells and tumor-derived cell lines." (PMID 22505999, 2012). "The tumor cells themselves primarily expressed only low levels of Cav-1 protein however some regions of the PMT had clusters of cells that stained positive for Cav-1 (arrowhead)." (PMID 22356861, 2012).